PRKAR1A (protein kinase cAMP-dependent type I regulatory subunit alpha)
Diseases named in the same sentence as PRKAR1A in open-access papers (continued):
Sharing a sentence is not in itself a finding about the gene and the disease.
acrodysostosis (continued). "Mutations in PRKAR1A have been associated with Acrodysostosis, a genetic disorder of bone growth." (PMID 25609184, 2015). "We identified a missense PRKAR1A mutation in a Chinese acrodysostosis patient with concomitant multiple hormone resistance, which was the first PRKAR1A mutation identified in a Chinese acrodysostosis patient." (PMID 25075981, 2014). "Our findings further suggest that the c.866G>A/p.G289E mutation in the PRKAR1A gene may be the cause of acrodysostosis with concomitant multiple hormone resistance." (PMID 25075981, 2014). "Thus, it is difficult to distinguish acrodysostosis cases with PDE4D mutations from those with PRKAR1A mutations on the basis of clinical observation only." (PMID 24028571, 2013). "Similarly, researchers identified several individuals with de novo pathogenic germline variants in PRKAR1A that had acrodysostosis, an autosomal dominant disorder characterized by hormone resistance, brachydactyly, craniofacial abnormalities, and short stature." (PMID 38481146, 2024). "Carney Complex PRKAR1A mutations reduce the stability of RIα and therefore increase PKA action, while acrodysostosis PRKAR1A mutations result in cAMP-resistant PKA holoenzymes and thereby reduce PKA activity." (PMID 36313756, 2022). "Our results confirm that the p.G289E variation of PRKAR1A is responsible for acrodysostosis with concomitant multiple hormone resistance." (PMID 25075981, 2014). "In order to improve our understanding, it will be important to develop cell, tissue and organism level models of acrodysostosis as this will allow for the understanding of how iPPSD5 manifests in the affected tissues as well as the changes mutations cause in PDE4D and PRKAR1A activity." (PMID 38983619, 2024). "However, unlike PRMT7-related disorder, these are all autosomal dominant disorders caused by heterozygous variants in GNAS (PHP 1A and 1C), PRKAR1A and PDE4D (acrodysostosis), and/or 2q37 deletion resulting in loss of the HDAC4." (PMID 36399134, 2023). "TSH resistance is present in patients with acrodysostosis owing to PRKAR1A mutations but not in those with PDE4D mutations." (PMID 29959430, 2018). "In addition, heterozygous mutations in PRKAR1A, which encodes the regulatory subunit of protein kinase A (PKA) and PDE4D, which encodes phosphodiesterase type 4, have been found in patients with acrodysostosis." (PMID 29280743, 2017). "In the past, the two subtypes of acrodysostosis were mainly differentiated by the presence or absence of hormonal resistance that was exclusively attributed to PRKAR1A mutations." (PMID 28515031, 2017). "The PRKAR1A gene and PDE4D gene have been found to be causative genes of acrodysostosis." (PMID 25075981, 2014). "We molecularly diagnosed mutations in CASR, KMT2D, GNAS, PRKAR1A, and CYP27B1, corresponding to cases with clinical diagnoses of isolated hypoparathyroidism/primary hyperparathyroidism, syndromic hypoparathyroidism, pseudohypoparathyroidism, acrodysostosis, and calcipenic rickets." (PMID 41155848, 2025). "Unlike Carney complex, many of the pathogenic variants in PRKAR1A that are found in patients with acrodysostosis may lead to decreased sensitivity to cAMP, resulting in a dominant negative effect on PKA activity (reviewed in Michot 2018)." (PMID 38481146, 2024). "PTH resistance and brachydactyly (but in a more severe form) are also present in acrodysostosis with multihormonal resistance ACRDYS1 (or iPPSD4, OMIM#101800), which is associated with mutations in the gene coding for the cAMP-dependent protein kinase type 1 regulatory subunit protein (PRKAR1A)." (PMID 29499646, 2018). "Recently, genetic defects in cAMP-dependent protein kinase type 1-α regulatory subunit (PRKAR1A) and cAMP-specific phosphodiesterase 4D (PDE4D) were identified in patients with acrodysostosis by candidate gene analysis and exome sequencing respectively." (PMID 28515031, 2017).
primary pigmented nodular adrenocortical disease (14 papers, 2014 to 2026). A form of bilateral adrenocortical hyperplasia that is often associated with adrenocorticotrophin hormone (ACTH) independent Cushing syndrome and is characterized by small to normal sized adrenal glands containing multiple small cortical pigmented nodules (less than 1 cm in diameter). "Apart from PRKAR1A variants in the subset of cyclical Cushing’s syndrome related to primary pigmented nodular adrenocortical disease and a case study raising a putative link between AHR and cyclical Cushing’s disease, there are currently no genes implicated in cyclical Cushing’s syndrome." (PMID 38075079, 2023). "PRKAR1A has been reported as a driver gene of ACC in a previous report, and germline variant is known as the cause for the Carney complex, or primary pigmented nodular adrenocortical disease (PPNAD)." (PMID 32287321, 2020). "Inactivating mutation of the cAMP-dependent protein kinase type 1α regulatory subunit (PRKAR1A) is responsible for both primary pigmented nodular adrenocortical disease (PPNAD) and the Carney complex." (PMID 30670014, 2019). "In primary pigmented nodular adrenocortical disease (PPNAD), germline inactivating mutations of the protein kinase A regulatory subunit type 1 (PRKAR1A)-linked cAMP-dependent protein kinase (PKA) to adrenocortical tumors (ACTs)." (PMID 27625633, 2016). "More than 70% of patients diagnosed with CNC carry mutations in the PRKAR1A gene (the “CNC1 locus”); the frequency increases to 80% in patients with Cushing syndrome due to primary pigmented nodular adrenocortical disease (PPNAD)." (PMID 40777560, 2025). "Inactivating mutations of the PRKAR1A gene, coding for the type 1A regulatory subunit of PKA, are responsible for Carney complex and primary pigmented nodular adrenocortical disease (PPNAD)." (PMID 26042218, 2015). "The only known genetic cause of CCS is germline PRKAR1A mutations causing Carney’s complex, including the common manifestation of ACTH-independent CCS due to primary pigmented nodular adrenocortical disease (PPNAD)." (PMID 31996203, 2020).
Cushing syndrome (13 papers, 2006 to 2026). Cushing's syndrome (CS) encompasses a group of hormonal disorders caused by prolonged and high exposure levels to glucocorticoids that can be of either endogenous (adrenal cortex production) or exogenous (iatrogenic) origin. "In CNC patients with Cushing's syndrome the frequency of PRKAR1A mutations is about 80 %, suggesting that families with PPNAD are more likely to carry a 17q22-24 defect." (PMID 16756677, 2006). "Among CNC patients with Cushing's syndrome, the frequency of PRKAR1A mutations is about 80%." (PMID 20548949, 2010). "Benign adrenal cortical tumors presenting with Cushing syndrome often have diverse mutations (PRKACA, PRKAR1A, GNAS, PDE11A, and PDE8B) involving the cyclic AMP signaling pathway." (PMID 29594118, 2018). "Mutations in PRKAR1A, PDE11A, and PDE8B have all been implicated in the pathogenesis of bilateral micronodular adrenocortical disease presenting with Cushing syndrome." (PMID 29594118, 2018). "Inactivating mutations in PRKAR1A, a gene encoding the type 1 α-regulatory subunit (R1α) of the cAMP–dependent protein kinase (PKA) have been found in 80% of CNC patients with Cushing's syndrome." (PMID 20548949, 2010). "Adrenal cortex-specific Prkar1a knockout mice (AdKO) develop pituitary-independent Cushing's syndrome and evident signs of deregulated adreno-cortical cells differentiation and hyperplasia." (PMID 20548949, 2010). "Somatic alterations of PRKAR1A were also described in CPAs, with LOH in the PRKAR1A locus 17q found in 7 of the 29 studied adenomas and somatic-inactivating mutations in 3 CPAs responsible for overt Cushing syndrome." (PMID 32783015, 2020). "Apart from PRKAR1A mutations in a subset of cyclical Cushing’s syndrome due to primary pigmented nodular adrenocortical disease, the molecular basis of cyclical Cushing’s syndrome has not been investigated." (PMID 31996203, 2020). "PRKAR1A inactivation and PKA dysregulation have been implicated in various types of adrenocortical pathologies associated with ACTH-independent Cushing syndrome (AICS) from PPNAD to adrenocortical adenomas and cancer, and other forms of bilateral adrenocortical hyperplasias (BAH)." (PMID 26042218, 2015). "No clear adrenal lesions nor Cushing's syndrome were observed in mouse models of haploinsufficiency, suggesting that complete loss of Prkar1a might be required to phenocopy human phenotype." (PMID 20548949, 2010). "Alteration of the repartition of fat depots is one of the features of “classic” Cushing's syndrome and is observed in PPNAD patients with PRKAR1A inactivation." (PMID 20548949, 2010).
myxoma (13 papers, 2011 to 2025). A benign soft tissue neoplasm characterized by the presence of spindle and stellate cells, lobulated growth pattern, and myxoid stroma formation. "Sanger sequencing analysis of myxoma samples identified six PRKAR1A mutations that were consistent with the PRKAR1A variant mutations detected by targeted NGS analysis." (PMID 38310436, 2023). "The PRKAR1A variants identified by Sanger sequencing analysis were consistent with those from the NGS analysis for the four myxoma specimens." (PMID 38310436, 2023). "A novel, large deletion upstream of the PRKAR1A gene was proved to be the cause of familiar myxoma which can be considered as Carney complex." (PMID 37670105, 2023). "The mutation in PRKAR1A causes myxomas and carney complex, and multiple myxomas are a feature of Carney complex." (PMID 38110859, 2023). "PRKAR1A gene sequencing analysis in their study further confirmed that 67% of CNC myxomas and 31% of isolated myxomas had pathogenic PRKAR1A mutations." (PMID 38310436, 2023). "Carney complex is inherited in an autosomal dominant fashion due in most cases to inactivating mutations of the PRKAR1A gene and is characterized by pigmented lesions of the skin, myxomas (cardiac and cutaneous), and multiple endocrine tumors." (PMID 31874650, 2019). "Recent data suggest that the loss of PRKAR1A protein expression may play a role in isolated myxoma tumorigenesis." (PMID 38310436, 2023). "Moreover, myxomas, acromegaly, and other symptoms are more common in patients with exon mutations than in those with PRKAR1A defects." (PMID 36092889, 2022). "Studies have implicated recurrent somatic mutations in PRKAR1A, as well as alterations in cAMP pathway genes such as PRKACA and PDE11A, suggesting a shared pathogenic mechanism between sporadic and familial myxomas." (PMID 40264618, 2025). "And the immunoblotting figures showed the expression of KIF1C and PRKAR1A in all myxoma tissues was lower than that in normal atrial tissues." (PMID 37452081, 2023). "The mutated PRKAR1A also causes other tumors including thyroid tumors because of increase in gene expression of RET/PTC2 signaling, multiple endocrine neoplasias and myxomas." (PMID 38110859, 2023). "A PRKAR1A was detected in this patient, her sister, and mother, but only the patient had an external auditory myxomas." (PMID 36092889, 2022). "Whole exome sequencing of her tumor revealed multiple mutations in PRKAR1A not found in her germline deoxyribonucleic acid (DNA), suggesting that the myxoma in this patient was sporadic." (PMID 31874650, 2019). "Mutations in PRKAR1A, a PKA-regulatory subunit, cause an inherited syndrome called the Carney complex, characterized by pigmented skin lesions, schwannomas, recurrent mucocutaneous myxomas and endocrine neoplasms." (PMID 24148783, 2013). "The CCDS of KIF1C (CCDS11065) was sequenced in cDNA samples that were extracted from myxoma tissues in patients without PRKAR1A variations in the validation group." (PMID 37452081, 2023). "Yinet al32 reported that mice lacking PRKAR1A protein specifically in cardiomyocytes ultimately develop heart failure and myxoma-like phenotype." (PMID 38310436, 2023). "Direct modification of Prkar1a expression is likely not the best therapeutic option for development in patients as it can result in the formation of myxomas in internal organs due to Carney complex complications." (PMID 32735622, 2020). "While PRKAR1A, PIK3CA (Q546E) and KRAS mutation (G12V), mutations have been detected in a minority of OMs and GNAS1 mutations are well described in intramuscular myxomas, neither has emerged as a consistent molecular feature of OMs." (PMID 41364259, 2025).
adenoma (10 papers, 2016 to 2026). A neoplasm arising from the epithelium. "In this setting, Cushing’s disease has been described in one adult and one pediatric patient carrying a germline PRKAR1A mutation; loss of heterozygosity was reported as the pathogenetic mechanism of adenoma formation." (PMID 35743266, 2022). "In a cohort of patients with 44 sporadic adrenocortical tumors (29 adenomas and 15 cancers), losses in 17q22-24 were found in 23% of the adenomas and 53% of cancers, while inactivating variants in the PRKAR1A gene were identified in three tumors." (PMID 35625779, 2022). "Somatic activating GNAS mutations and somatic allelic loses of PRKAR1A were seen in up to 17 and 23% of glucocorticoid-producing adenomas, respectively." (PMID 29594118, 2018). "In a study including 44 sporadic adrenocortical tumors (29 adenomas and 15 cancers), 17q22-24 losses were noted in 23% of adenomas and 53% of cancers, with inactivating PRKAR1A mutations identified in three tumors." (PMID 30456751, 2018). "In addition to the cAMP/PKA pathway, involvement of the Wnt/beta-catenin pathway was also reported in a study including 13 patients with PPNAD or sporadic cortisol-secreting adenomas (ACAs) with PRKAR1A somatic mutation." (PMID 32783015, 2020). "Interestingly, glucocorticoid-producing adenomas with somatic PRKAR1A alterations were more frequently associated with smaller tumor size and paradoxical increase in urinary cortisol levels following dexamethasone suppression." (PMID 29594118, 2018). "Whole-animal homozygous knockouts of Prkar1a are lethal, but tissue-specific Prkar1a knockouts in each of pituitary, adrenal cortex, and pancreatic neuroendocrine tissue develop hyperplasia and adenomas in these tissues, respectively." (PMID 36313756, 2022). "Increased cAMP signaling was demonstrated due to significant Prkar1a downregulation and the mice exhibited a more severe phenotype with high incidence of thyroid lesions (thyroid follicular hyperplasia and adenomas)." (PMID 34359735, 2021). "Conversely, no concomitant CTNNB1, PRKACA, PRKAR1A or GNAS somatic variant (classically met in cortisol-producing adenomas) with a germline ARMC5 alteration has been yet reported to our knowledge." (PMID 39910635, 2025). "Additionally, 99% of adenomas bearing mutations in cAMP/PKA pathway-related genes (PRKACA, GNAS, or PRKAR1A) displayed high StAR expression." (PMID 27606678, 2016).
breast carcinoma (9 papers, 2015 to 2024). "PRKAR1A is associated with poor patient prognosis in basal‐like breast cancer, and low PRKAR1A/high SRC expression has been linked to basal‐like and HER2+ breast cancers with adverse clinical outcome." (PMID 35000262, 2022). "Moreover, the gene encoding for the four regulatory units of the enzyme, PRKAR1A, which negatively regulate the catalytic subunit, is commonly amplified in human breast cancers." (PMID 37504297, 2023). "Previous studies have implicated abnormalities in Axin1 and Prkar1a expression in breast cancer although their roles in normal development and oncogenesis remain unclear." (PMID 35000262, 2022). "The clinical results confirmed PRKAR1A expression in various cancer types, including lung adenocarcinoma, lung squamous cell carcinoma, liver hepatocellular carcinoma, and breast cancer." (PMID 38474121, 2024). "Further studies will be required to define the precise roles of Axin1 and Prkar1a in breast epithelial cells and the mechanisms by which defects in these genes contribute to breast cancer progression." (PMID 35000262, 2022). "Pertinently, deletion of Prkar1a alone in mouse mammary glands led to mammary tumors, albeit with a latency of ~ 12 months." (PMID 35000262, 2022). "Reduced protein abundance of the regulatory PKA subunit PRKAR1A was reproducible in other breast cancer cell lines, though mRNA levels were unaltered." (PMID 26203557, 2015). "Analysis of differential expression levels highlighted CLDND1, PLEKHA2, ACSL3, SLC30A9, MSN, CALM3 and PRKAR1A as potential regulators of breast cancer cell survival since they were affected by PKCδ siRNA in all cell lines." (PMID 26083392, 2015). "Low PRKAR1A/high SRC mRNA has been shown to define basal‐like and HER2‐positive breast cancers with a worse clinical outcome, and PKA activity has also been implicated in HER2 resistance in vitro, in particular down‐regulation of the PKA‐RIIα subunit." (PMID 33991172, 2021). "Since miR-1246 was expressed higher in ER- breast cancer subtypes and induced pro-inflammatory responses in MSCs by targeting PRKAR1A and PPP2CB, we hypothesized potential roles of PRKAR1A and PPP2CB as tumor-suppressors in breast cancer." (PMID 28159925, 2017). "In addition, PRKAR1A and PPP2CB negatively correlated with miR-1246 expression, indicating that miR-1246 could regulate both targets in tumors of breast cancer patients." (PMID 28159925, 2017). "Analysis of expression in the TCGA confirmed lower expression of PRKAR1A in the basal‐like subtype and showed that AXIN1 levels did not change appreciably across subtypes of breast cancer." (PMID 35000262, 2022).
thyroid cancer (9 papers, 2014 to 2024). "Possible mechanisms of hyperthyroidism in patients with thyroid carcinoma include somatic mutations in the gene for thyrotropin receptor (TSHR) or mutations in the PRKAR1A gene." (PMID 39049862, 2024). "CNC is caused by inactivating mutations in the PRKAR1A gene (mapped in 17q22–24); somatic mutations in this gene have been reported in sporadic cases of thyroid cancer." (PMID 34359735, 2021). "PubMed was used to investigate the relevant terms and combinations: “thyroid carcinoma,” “PRKAR1A,” "carney complex,” “thyroid cancer” AND “carney complex,” “PRKAR1A mutation” AND “protein kinase A.” In this instance, only results in the English language were displayed." (PMID 38074042, 2023). "Among the genes associated with thyroid cancer BRAF, RAS, KRAS, NRAS, PTEN, and PRKAR1A genes participate in regulating oxidative metabolism." (PMID 39180118, 2024). "PRKAR1A, a pivotal regulator of PKA activity, potentially plays a role in the intricate molecular mechanisms that underlie the pathogenesis of thyroid cancer associated with CNC." (PMID 38074042, 2023). "In conventional Prkar1a heterozygous mouse models, about 11% of mice older than 13.5 months of age developed malignant thyroid neoplasms." (PMID 37446316, 2023). "It was shown that Prkar1a haploinsufficiency leads to tumor development arising in cAMP-responsive tissues, including among others, benign and malignant thyroid neoplasms." (PMID 34359735, 2021). "The data also suggests that patients with CNC are more susceptible to the development of thyroid carcinoma than those without, and patients with a PRKAR1A mutation are at a higher risk of developing thyroid tumors." (PMID 29666959, 2018). "PRKAR1A, a regulator of PKA activity, is possibly involved in the molecular events that contribute to thyroid cancer." (PMID 34359735, 2021). "The age at onset of thyroid cancer in two Japanese CNC patients was 72 and 73 years old, in whom PRKAR1A mutation was negative in one and not available in the other." (PMID 29666959, 2018).